CD4 (CD4 molecule)
Diseases named in the same sentence as CD4 in open-access papers (continued):
Sharing a sentence is not in itself a finding about the gene and the disease.
influenza (continued). "Transferring activated CD4+ T-cells protects mice from lethal influenza infections." (PMID 39066433, 2024). "Furthermore, introduction of influenza antigens induced more Th1 CD4 T cells in tonsil organoids from pediatric female donors." (PMID 38812520, 2024). "However, additional studies are needed to assess the direct impact of heterologous infection or immunization priming of CD4+ T cells on survival, protection, or enhancing production of cross-reactive high affinity antibodies in response to influenza challenge." (PMID 39283916, 2024). "Efforts into producing a more effective influenza vaccine have found that an intranasal nanoparticle vaccination elicited a persistent, polyfunctional CD4+ T cell response producing IFNγ and TNFα in murine models, which mediates survival from a lethal challenge with H1N1 influenza virus." (PMID 38317404, 2024). "However, all influenza antigens (including both vaccines and both viruses) elicited a preferential expansion of Th1 CD4 T cells in female-derived organoids compared to male-derived organoids." (PMID 38812520, 2024). "Cumulatively, these data indicate that unlike CMV vector-mediated protection against SIV replication, protection against lethal HPAI infection does not depend on CD8 + T cells, regardless of their MHC restriction, but rather on the magnitude of influenza-specific CD4 + T cell prior to infection." (PMID 39030218, 2024). "Therefore, to better understand the impact of CD4+/CD25+FoxP3+ Tregs on influenza disease progression, Tregs were induced by high dose IAV infection." (PMID 38979428, 2024). "Similar to 8 days after influenza challenge, heterologously primed mice maintained significantly higher frequencies and numbers of I-Ab:gp66-77 tetramer+ CD4+ T cells in medLN 42 days after influenza challenge compared to the unprimed PR8(1°) and homologously primed PR8(1°)PR8(2°) groups." (PMID 39283916, 2024). "Our study specifically aimed to investigate whether altering the magnitude of memory CD4+ T cell help in the GC reaction would enhance the generation of antiviral humoral immunity to primary influenza infection." (PMID 39283916, 2024). "During influenza infection, virus antigens are presented to CD4+ T cells for over 7 days." (PMID 39452110, 2024). "In agreement with the idea that Tfh cells are the limiting cell subset in the GC reaction and the generation of GC-derived products, following heterologous influenza rechallenge of memory CD4+ T cells we saw an early increased magnitude of antigen-specific GC Tfh and GC B cells." (PMID 39283916, 2024). "The expression of interferon response genes STAT1, STAT2, Mx1, OASL2, ISG15, chemokines CCL2, CCL3, CXCL9 and CXCL10, and the frequency of neutrophils (CD45+CD11b+Ly6G+) and CD4+ T cells (CD45+CD4+) were all significantly increased in influenza-infected mice when compared to vehicle controls." (PMID 38750107, 2024). "These arrays of features suggest that R-DOTAP is a promising candidate for inducing CD4+ T cell responses that could convey protective immunity to pathogens such as influenza." (PMID 38543915, 2024). "Consequently, influenza antigen-induced Th1 CD4 T cells, along with the augmented surveillance of lymphoid tissues by memory CD4 T cell subsets, can collectively contribute to the heightened adaptive immune response observed in females." (PMID 38812520, 2024). "Moreover, post-vaccine levels of influenza antibodies were shown to inversely correlate with CD4 T cell activation that, in turn, positively correlated with pre-vaccine plasma levels of TNF32." (PMID 39587133, 2024). "Challenge studies have demonstrated that pre‐existing CD4+ T cells confer lower viral shedding and less severe illness during influenza infection, and the 2009 influenza pandemic revealed that pre‐existing T cells to conserved CD8 epitopes were correlated with less severe illness." (PMID 39440808, 2024).
influenza (continued). "Our study showed that heterologous priming induced an increase in both CD4+ T and B cells early following influenza infection, suggesting we could successfully target enhancement of the germinal center." (PMID 39283916, 2024). "In addition, vaccination with influenza HA-ferritin nanoparticles showed a positive correlation between increased ferritin-specific CD4+ GC Tfh cells and increased HA-specific GC B cells and antibody secreting cells." (PMID 39283916, 2024). "A week after influenza infection, a robust influx of CD4+ and CD8+ T cells is observed." (PMID 37696824, 2023). "Both blood datasets revealed decreased adaptive immune responses and co-stimulation in B cells, as well as decreased levels in cellular responsiveness, and pathways related to infectious disease and influenza responses in both CD4 and CD8 T cells in Dex patients." (PMID 37577607, 2023). "In influenza and hepatitis C viral infections too, lung epithelial cells and hepatocytes upregulate cell-surface expression of HLA class II molecules, becoming targets for cytolytic CD4+ T cells." (PMID 38001069, 2023). "We considered the possibility that loss of Aiolos may result in alterations to regulatory CD4+ T cell populations, as this could impact both TFH differentiation and influenza-specific antibody production." (PMID 36964178, 2023). "Influenza vaccine-mediated protection is dependent on CD4+ T cells, influenza-specific CD4+ memory T cells, which have the potential to overcome the poor immunogenicity of vaccines, which is needed for early antibody production and CD8+ T cell recall responses." (PMID 36960292, 2023). "Indeed, inactivated influenza presents CD4 antigens for only a few days, producing mostly Th0 and Th1 effectors in the SLO with few TFH, limited generation of B-cell Ab." (PMID 38152398, 2023). "Furthermore, cTfh cells isolated from influenza vaccine recipients have been shown to preferentially differentiate B cells and stimulate influenza-specific antibody secretion over other CD4+ T cell subsets." (PMID 37063867, 2023). "Recently, we followed CD4 effector fate in vivo after influenza infection and analyzed the signals from infection responsible for rescuing effectors from default apoptosis so that they could become memory cells." (PMID 38152398, 2023). "Importantly, influenza-specific CD4+ T cells have been correlated with protection against disease even in humans lacking cross-protective antibodies." (PMID 37112974, 2023). "In addition, memory CD4+ T cells not only support B cells but also cytotoxic responses during influenza infection." (PMID 36986773, 2023). "Influenza-specific CD4 T cells also play key additional roles in the immune response to influenza." (PMID 35215193, 2022). "Influenza vaccine treatment was also associated with appreciable CD4+ T-cell activation, despite a lack of viral RNA release." (PMID 35985993, 2022). "Since aged mice nonetheless develop a robust iABC in response to influenza, we hypothesized that this subset is less dependent on CD4 T cell help." (PMID 36056604, 2022). "Sex, age, underlying disease, use of immunosuppressant and steroids, and CD4+ T-cell count did not affect the incidence of influenza-associated aspergillosis." (PMID 35628717, 2022). "In addition, after stimulating CD4+CXCR5+Tfh cells with an influenza antigen, it was found that the level of CD40 L in the OS group was significantly reduced and the level of IFNγ was increased considerably." (PMID 35494526, 2022). "Although the loss of CCR2 impairs CD8+ TRM cell accumulation in influenza models, CD4+ TRM cell accumulation after pneumococcal pneumonia did not depend on this chemokine receptor." (PMID 35133985, 2022). "Priming of the fetal immune system to B. pertussis antigens after vaccination in pregnancy is important to investigate given that influenza vaccination in pregnancy leads to fetal production of influenza-specific IgM antibodies and influenza-specific CD4+ T cells detected in the cord." (PMID 36560400, 2022).
influenza (continued). "Since B-2 B cells undergo isotype switching and affinity maturation depending on helper viral antigen specific CD4+ T cells, we next followed how influenza antigen specific CD4+ T cells accumulate inside the lung draining MedLNs of virus infected ICAM-1/2-/- mice." (PMID 36895258, 2022). "Using influenza HA-ferritin nanoparticles as a prototype, we have performed an unbiased assessment of the CD4 T cell epitope composition of the ferritin particles relative to that contributed by influenza HA using mouse models that express distinct constellations of MHC class II molecules." (PMID 36289232, 2022). "Experimental studies in mice and studies of the virus-specific T-cell response in humans have shown that the combination of non-neutralizing antibodies with CD8+ and CD4+ T cells can provide protection against highly pathogenic influenza infection." (PMID 36560509, 2022). "The stimulation/recall of antigen-specific memory CD4+ T cells, derived from previous influenza infections or vaccinations, was assessed by the frequencies of cytokine-secreting central memory (CM) and effector memory (EM) T cell populations (CD45RA- CCR7+ and CD45RA- CCR7-, respectively)." (PMID 36371426, 2022). "A similar phenotype is observed for adoptively transferred influenza-specific memory CD4+ T cells." (PMID 35880171, 2022). "Moreover, both the 500 nm and 3 μm influenza conjugates induced significantly higher numbers of cytokine-producing CD4+ T cells and induced increased production of the pro-inflammatory cytokines IFNγ and TNFα." (PMID 35890185, 2022). "This was demonstrated during the 2013 H7N9 influenza outbreak, where a shorter recovery time from severe H7N9 disease was associated with early and robust CD8+ T cell responses, and prolonged hospital stays with late recruitment of CD4+ and CD8+ T cells." (PMID 35603215, 2022). "Recent evidence also suggests that CD4 cells reacting to peptides from core viral proteins such as NP and M1 are first responders to influenza challenge and can have important effector functions of their own, as they contain perforin and granzyme and produce IFN-γ." (PMID 35051231, 2022). "Moreover, immune stability positively correlated to an increase in CXCR5+ CD38+ CD4+ T cells 7 days after influenza vaccination, negatively correlated to age, and was immunotype‐dependent." (PMID 36081314, 2022). "Furthermore, the results also showed that influenza patients had higher percentages of cycling CD4+ T cells than normal controls." (PMID 36064355, 2022). "Next generation influenza vaccine strategies should also consider the quantitative and qualitative features of the CD4 T cell repertoire that respond to vaccination, and how they may shape the germinal center response." (PMID 36289232, 2022). "Mild to moderate influenza and SARS-CoV-2 infections are associated with prototypical antiviral immune responses involving transient, co-ordinated activation and contraction of virus-specific CD4+ and CD8+ T cells, B cells and antibodies." (PMID 35603215, 2022). "Notably, heterogenous populations of influenza-specific memory CD4+ TRM cells in mice lungs was reported to clear the infection and increased survival, independent of CD8+ T cells or B cells." (PMID 36211412, 2022). "Next, we investigated whether Bach2-deficiency in regulatory T cells altered the activation and expansion of effector CD8 and CD4 T cells during an influenza infection." (PMID 36033397, 2022). "As a result of the critical role that CD4 T cells play in protective immunity to influenza and other respiratory pathogens, the ability to track and analyze the specific CD4 T cell responses to infection or responses after vaccination to influenza virus challenge is critical." (PMID 35215193, 2022). "Interestingly, the tissue-specific gene module derived from lung in the context of influenza infection was also significantly upregulated by all subtypes of LCMV-specific CD4+ T cells in the liver, compared to those from spleen." (PMID 35829695, 2022).
influenza (continued). "Thus, we performed heterochronic (age-mismatched) adoptive transfer of 1 × 106 splenic young or aged Treg cells (~90% CD4+CD25hiFoxp3+) via retro-orbital injection into aged or young mice 24 hours after influenza infection." (PMID 33600379, 2021). "Enhanced stimulation of the expansion of CD4+ T cells, which is critical for protecting the lungs from viral replication along with triggering robust antibody responses, results in higher levels of cross-reactive CD4+ T cells with a greater ability to recognize novel influenza strains." (PMID 34207924, 2021). "Taken together, the ICOS+CD38++ influenza-specific CD4 T cell population that shapes the “early” activation response after seasonal influenza vaccination is characterized by high metabolic demands and phenotypic and transcriptional markers of Tfh differentiation." (PMID 34795301, 2021). "Robust haemagglutinin (HA)-specific CD4+ T cells’ response to seasonal influenza vaccination." (PMID 34726156, 2021). "We also reproduced the population dynamics of CD4+ T cells during influenza infection." (PMID 34343169, 2021). "Available evidence suggests that an inverted CD4+ to CD8+ T –cell ratio may indicate an impaired ability to respond to repeated antigenic stimulation in the setting of influenza vaccination." (PMID 34925330, 2021). "In mice, the peak CD4+ T cell response is observed at 10 days post influenza infection." (PMID 35222350, 2021). "Total CD4 T cell reactivity at any time point was defined as the total number of cells that produce any of the 4 effector responses (IFNγ, Granzyme B, IL-4 and IL-10) to the different MPs from all 4 influenza strains." (PMID 33922875, 2021). "Moreover, polyfunctional Th1 and Th17 cell subsets were underrepresented in the repertoire of SARS-CoV-2-reactive CD4 + T cells compared to influenza-reactive CD4 + T cells." (PMID 34064728, 2021). "In mice, some perforin-expressing effector CD4+ T cells protect against lethal influenza infection." (PMID 34445118, 2021). "The specific phenotype of the T CD4+ recruited via CCR5 during influenza is yet to be defined." (PMID 35126379, 2021). "In addition to M2e specific antibodies, protection against influenza is highly dependent on CD4+ T cells and recovery following influenza infection is highly dependent on CD8+ T cells." (PMID 34835255, 2021). "Next, we evaluated the cytokine polarization of the cellular responses of Flucelvax, and consistent with what was found in pre-existing influenza-specific responses at baseline, vaccine-specific CD4 T cells produced primarily IFNγ cytokines and exhibited a dominant Th1 polarized profile." (PMID 33922875, 2021). "Similarly, analysis of CD27/CD45RA/CD95 phenotypes showed significant differences in the activation of tetramer+ CD8+ and CD4+ T cells in influenza+ patients when compared to the parental CD8+ and CD4+ T cell populations at acute and follow-up timepoints." (PMID 33976217, 2021). "Therefore, seasonal influenza vaccination increases anti-HA IgG titres, induces a cTfh response, and promotes the expansion and differentiation of HA-specific CD4+ T cells." (PMID 34726156, 2021). "The expression levels of the main surface markers characterizing peripheral Tfh and Th1 cells (i.e. CXCR5, PD-1 and CXCR3) are shown on HCV-specific CD4 T cells in comparison to influenza- (Flu-) specific CD4 T cells ex vivo in a representative HCV-infected, DAA-cured or healthy donor, respectively." (PMID 34659236, 2021). "Also, it was previously demonstrated that the CD4+ T-cells can possess a cytolytic function on influenza-infected cells in mice, other than their classical helper role." (PMID 32344753, 2020). "Human Th1 CD4+ T cells have been particularly well studied in the context of influenza." (PMID 33374787, 2020).
influenza (continued). "We transfected three independent cell lines (each presenting a different IEd-restricted influenza epitope) with C15-HA, sorted populations based on HA tag expression, and subsequently co-cultured the sorted populations overnight with CD4+ T cell hybridomas recognizing each of the three epitopes." (PMID 32745153, 2020). "Although our cohort was heterogeneous, the participants had weak haemagglutination-inhibition antibody immune responses after vaccination with the inactivated influenza vaccine despite having generally normal CD4 cell counts and a high proportion being on antiretroviral therapy (ART)." (PMID 31911146, 2020). "However, the role of CD4 and its impact on influenza in HIV-positive patients is poorly understood, partly due to their heterogeneity and lack of epitope-specific systems." (PMID 33392051, 2020). "Our finding on CD4+ T cells is consistent with a previous report confirming that pre-existing memory CD4+ T cells (and not CD8+ T cells or Abs) are responsible also for limiting the severity of illness caused by influenza." (PMID 32463814, 2020). "Inhibition of such alternative activation of ERK, JNK and p38 in aged mice increased both CD4+ T-cell and B-cell response to influenza vaccination, suggesting that MAPKs may be targeted to improve influenza vaccine efficacy in the elderly." (PMID 32709018, 2020). "Taken together, we present an approach for identifying novel influenza virus–reactive CD4+ T cell subsets, a method that could help advance understanding of the immune response to influenza, predict responsiveness to vaccines, and aid in better vaccine design." (PMID 33310880, 2020). "However, there is increasing evidence that endogenous MHCII antigen processing and presentation by a directly infected cell can drive CD4+ T cell activation and, in the case of influenza, accounts for the large majority of CD4+ T cell expansion." (PMID 32745153, 2020). "To investigate this further, we assessed whether P11 or P35 were CD4 T cell epitopes in influenza-infected c57BL/6 mice using our recently developed activation-induced marker (AIM) assay." (PMID 33137148, 2020). "CD4+ T cell responses peak at 10 days after influenza infection in the mouse lung." (PMID 32375274, 2020). "Importantly, our studies have shown that the CTL response to ex vivo influenza challenge is dependent on the presence of CD4 T cells in the PBMC cultures." (PMID 32399058, 2020). "In contrast, sPD-1 co-electroporation elevated HA-specific CD4+ T cell responses, decreased regulatory CD4+ T cell pools, and modulated the IgG2a-biased HA antibody pattern towards an isotype-balanced IgG response with a trend to higher influenza neutralization in vitro." (PMID 33019546, 2020). "Influenza vaccine is recommended for all individuals >6 months of age in the US, EU, and also in Japan, but the split vaccine is less effective in young infants because its efficacy depends on the immunological CD4 memory." (PMID 32230902, 2020). "Our study shows that influenza infection elicited T-cell responses primarily for CD4+." (PMID 32572168, 2020). "Additionally, influenza-specific CD4+ T cells correlate with protection against influenza challenge in humans." (PMID 32802896, 2020). "However, when comparing the mice that were infected with influenza (VC/PR8 vs. TCS/PR8) there was a reduction in the total number of CD44hi CD4+ T cells in the lung and BAL of the TCS exposed mice." (PMID 33373420, 2020). "In addition, during influenza infection pDCs are capable of priming primary and secondary CD4 and CD8 T cell responses in vitro and in vivo." (PMID 32463814, 2020). "Here, we used ex vivo stimulation of memory T cells and screening of naive and memory T cell libraries, combined with T cell cloning and TCR sequencing, to dissect the human naive and memory CD4+ T cell repertoire against the influenza pandemic H1 hemagglutinin (H1-HA)." (PMID 32644114, 2020).